RHOC (ras homolog family member C)
Diseases named in the same sentence as RHOC in open-access papers (continued):
Sharing a sentence is not in itself a finding about the gene and the disease.
colorectal cancer (10 papers, 2009 to 2021). A primary or metastatic malignant neoplasm that affects the colon or rectum. "On the basis of in vitro results, the present study was aimed to determine whether the recombinant adenovirus mediated 4-tandem linked shRNA construct targeting RhoA and RhoC genes may inhibit the growth of human colorectal cancer cell graft implanted in nude mice in vivo." (PMID 20828398, 2010). "Beyond RHOB and RHOC, RNA editing of RHOQ and hypermethylation of RAC3 are associated with CRC and invasiveness in colorectal cancer cells." (PMID 33406731, 2021). "It has also been shown that the level of RhoA expression correlates with the histopathological degree of cancer, and RhoC expression correlates with the extent of local invasion in colorectal carcinoma patients." (PMID 33406809, 2021). "Among them, RhoA and RhoC genes are found to be overexpressed in colorectal cancer and are considered to be potential targets for the management of colorectal cancer." (PMID 29861465, 2018). "In agreement with this, RhoC expression and activation coincide with EMT of colorectal cancer cells that is associated with increased aggressiveness during tumorigenesis." (PMID 23144867, 2012). "RhoA and RhoC have been proved to be over-expressed in many solid cancers, including colorectal cancer." (PMID 20828398, 2010). "The present study was to evaluate the effect of silencing of RhoA and RhoC expression by RNAi on growth of human colorectal carcinoma (CRC) in tumor-bearing nude mice in vivo." (PMID 20828398, 2010). "In this study, for the first time we constructed adenovirus vector carrying RhoA and RhoC shRNAs in tandem expression and investigated the inhibitory effects of recombinant adenovirus on the cell proliferation and invasion of colorectal cancer HCT116 cells." (PMID 19374769, 2009). "In this study, for the first time we constructed recombinant adenovirus to investigate the inhibitory effects of RhoA and RhoC shRNAs in tandem expression on the cell proliferation and invasion of colorectal cancer HCT116 cells." (PMID 19374769, 2009). "Likewise, Rho GTPases such as RhoA, RhoC and Rac1 were found to be upregulated in colorectal carcinoma." (PMID 34151400, 2021). "RhoA and RhoC are deregulated by over expression in many human tumors, including colorectal cancer." (PMID 19374769, 2009). "We showed that a significant reduction in RhoA and RhoC expression could markedly inhibit the invasion and migration potentials of colorectal cancer cells." (PMID 19374769, 2009). "A study in colorectal cancer indicated a strong correlation of both RhoA and RhoC in metastasis and invasion, whereas other studies in breast and colon cancer have suggested that RhoA often inhibits cell invasion, while RhoC, on the other hand, enhances cell invasion." (PMID 31340863, 2019). "Our previous studies have also demonstrated that the over-expression of RhoA and RhoC occured in colorectal cancer tissues from Chinese patients and RhoA and RhoC shRNAs in tandem linked expression could markedly inhibit the invasion and migration potentials of colorectal cancer cells." (PMID 20828398, 2010). "Moreover, elevated RhoC expression has been found to correlate with poor outcome in whites with colorectal carcinoma and may be used as a prognostic marker of colorectal carcinoma." (PMID 19374769, 2009). "Examples discussed in this review include Cdc42, Rac1, RhoA, RhoC and RhoH activation of oncogenic STAT3, and in some cases STAT5, in a range of cancers including but not limited to: breast, bladder, gastric, cervical, myeloid, pancreatic, hepatocellular, head and neck, and colorectal cancer." (PMID 32915198, 2020).
bladder cancer (8 papers, 2010 to 2019). "RHOC has attracted attention as its increased expression has been linked to increased invasion and metastasis in bladder cancer." (PMID 22895562, 2012). "In addition, high RHOC protein levels have been previously associated with poorer disease-free and overall survival in bladder cancer patients." (PMID 22895562, 2012). "High RhoA and RhoC expression is correlated with poor tumor differentiation, muscle invasion, and lymph node metastasis in bladder carcinoma." (PMID 31108958, 2019). "It was found that miR-493 expression decreased in bladder cancer and overexpressed miR-493 suppressed bladder cancer cells motility through down-regulation of RhoC and FZD4." (PMID 26799283, 2016). "In particular, its expression is known to decrease cell growth and migration in bladder cancer by inhibiting targets RhoC and FDZ4." (PMID 25506832, 2014). "In the present study, we found marginally higher RHOC mRNA levels in the bladder cancer tissues compared to the normal tissues." (PMID 22895562, 2012). "Similarly, another study reported that the high-expression of RhoA and RhoC were associated not only with muscle invasion and LNM (P<0.001, P<0.05, respectively), but also with poorer survival in bladder cancer (P<0.0001)." (PMID 22860091, 2012). "Another miRNA with increased expression is miR-493, which is defined as a tumor suppressor in bladder cancer and is capable of downregulating FZD4 and RhoC protein expression." (PMID 23776562, 2013). "In conclusion, our data confirm the involvement of high VEGFA and OPN levels in bladder cancer, as well as an important role for FGF2 and RHOC in this disease." (PMID 22895562, 2012).
breast tumor (8 papers, 2002 to 2020). "Also, RhoC−/− mice show a much lower frequency of lung metastases from breast tumors caused by polyoma middle T-antigen expression despite similarly sized primary tumors." (PMID 27600078, 2016). "In support of RhoC as a mediator of chemoresistance, Kawata and colleagues separately found that RhoC protein expression was significantly higher in breast tumor tissue after chemotherapy compared with tumor tissue taken before therapy." (PMID 32992837, 2020). "Downregulation of c-Src/Twist or inhibition of miR-10b production results in HOXD10 upregulation and causes a decrease in the expression of RhoA/RhoC and a reduction of ROK-mediated breast tumor cell invasion." (PMID 27070574, 2016). "Twist overexpression promotes a cancer stem cell (CSC) phenotype and has also been shown to induce miR-10b, which inhibits the mRNA of HOXD10 and results in the increase of RhoC in CD44-positive breast tumor cells." (PMID 27070574, 2016). "ST-3 leads to an up-regulation of the small GTPases of the Rho family, RhoC and cdc42, which have an important role in cancer progression, including proliferation, invasion, and metastasis of breast tumours." (PMID 17233884, 2007). "These events lead to the reduction of the tumor suppressor protein, HOXD10, RhoA/RhoC overexpression, ROK activation, and breast tumor cell invasion." (PMID 27070574, 2016). "For breast tumours we found that there was only a tendency in the expression of rhoB, rhoC and rac1 mRNA, but not of rhoA mRNA, to increase with grading." (PMID 12237774, 2002).
cervical carcinoma (8 papers, 2010 to 2025). A carcinoma arising from either the exocervical squamous epithelium or the endocervical glandular epithelium. "In cervical cancer cells, Notch homolog 1, translocation-associated (Drosophila) (Notch1) and RhoC make similar phenotypic contributions to EMT, and Notch1 inhibition can reduce RhoC activity, suggesting that the latter plays a role as an effector of the former." (PMID 34627249, 2021). "Collectively, these results demonstrated that RAB33A promoted migration and invasion by increasing the levels of active RhoC in cervical cancer cells." (PMID 40000633, 2025). "Y-27632 inhibited ROCK1 in human cervical carcinoma (CaSki) cells with overexpressed RhoC that eventually led to decreases in the rate of invasiveness and migration." (PMID 32443784, 2020). "In cervical cancer, Notch1 has been proven to regulate RhoC leading to changes in migration and invasion." (PMID 31340863, 2019). "To further demonstrate the contribution of RhoC to radiation response in cervical carcinoma, we used RhoC siRNA-based knockdown to evaluate its effect on cell survival." (PMID 31488179, 2019). "We further investigated if ROCK2 and RhoC physically interact with each other in the nuclear compartment of the cervical cancer cells." (PMID 31488179, 2019). "Our key finding is that enhanced RhoC levels contribute to radioprotection in cervical cancer cells." (PMID 31488179, 2019). "Considering that RhoC regulates several tumor phenotypes in cervical cancer and other tumors, we decided to explore the role of RhoC as a modulator of radiation response in cervical cancer using cell lines and patient-derived cells." (PMID 31488179, 2019). "In cervical cancer, conditioned media from SiHa cells stably over-expressing the RhoC gene resulted in increased in vitro tube formation by HUVEC cells." (PMID 31340863, 2019). "This indicated that the RhoC overexpression regulates the DNA repair machinery in the cervical cancer cells." (PMID 31488179, 2019). "Further experiments were thus directed to discern the role of ROCK2 as the downstream effector of RhoC in cervical cancer radioresistance." (PMID 31488179, 2019). "RhoC also regulates EMT in cervical cancer, wherein the inhibition of Notch1 and RhoC resulted in the abolition of actin stress fiber formation and fibronectin expression, the two important changes associated with EMT." (PMID 31340863, 2019). "Our previous report shows that RhoC via Notch1 modulates angiogenesis, migration, invasion, metastasis, anoikis resistance and tumor growth in cervical cancer, leading to the progression of the disease." (PMID 31488179, 2019). "Combined, these findings begin to define the role of RhoC in DNA repair and radiation response in cervical cancer." (PMID 31488179, 2019). "Future work would aim at evaluating ROCK2 as a biomarker and therapeutic target in the context of radioresistance in cervical cancer and understanding the mechanistic of RhoC and ROCK2 in DNA repair regulation." (PMID 31488179, 2019). "Next, we demonstrated that indeed increased RhoC overexpression modulates the radioresistance of cervical cancer cell lines." (PMID 31488179, 2019). "A similar study performed on the cervical carcinoma model demonstrated that RhoC is necessary for TGF-β1 driven EMT." (PMID 31340863, 2019). "In cervical carcinoma cells, both Notch1 and RhoC have similar phenotypic contribution to EMT, and Notch1 inhibition decreases RhoC activity, suggesting that RhoC functions as an effector of Notch1." (PMID 24986540, 2014). "To assess the contribution of RhoC to invasion and metastasis, we used cervical carcinoma-derived CaSki and SiHa cells." (PMID 19953094, 2010). "Using CaSki and SiHa cells (cervical carcinoma cells lines), we show that RhoC contributes to wound healing, invasion and migration, anoikis resistance, colony formation, in vitro tube formation and tumour formation." (PMID 19953094, 2010).
cervical carcinoma (continued). "In accordance with its contribution to motility and invasion of several cancers, our data show that RhoC contributes to tumour progression by affecting invasion, anoikis resistance, tumour growth and angiogenesis in cervical carcinoma cell lines." (PMID 19953094, 2010). "To further corroborate our findings in a clinical setting, we examined the expression of RhoC and its relationship with Notch1 in archival cervical carcinoma specimens using immunohistochemical technique." (PMID 19953094, 2010). "This study has provided evidence to suggest that RhoC is an effector of Notch1 in cervical carcinoma." (PMID 19953094, 2010). "By linking the function of Notch and RhoC, we further strengthen the notion that there is a pro-oncogenic role of Notch signalling in human cervical cancers." (PMID 19953094, 2010). "Immunohistochemical analysis of archival tissue suggests a correlation between RhoC and Notch1 expression in human cervical carcinoma tissues." (PMID 19953094, 2010). "Next, we sought to investigate how RAB33A increases RhoC levels in cervical cancer cells." (PMID 40000633, 2025). "Our findings reveal a pivotal role of the RAB33A-RhoC axis in cervical cancer metastasis, indicating that RhoC inhibitors may be beneficial for treating cervical cancer patients with high levels of RAB33A." (PMID 40000633, 2025). "We have earlier published that RhoC regulates tumor progression in cervical cancer." (PMID 31488179, 2019). "Using immunohistochemical techniques, we show that there is expression of both Notch1 and RhoC in the same areas of cervical carcinoma tissue sections with significant correlation while there was negligible expression of the proteins in the normal cervical tissue sections." (PMID 19953094, 2010). "RhoC protein expression in cervical carcinoma cell lines was assessed by western blotting." (PMID 19953094, 2010). "Herein, we demonstrate that RAB33A promoted metastasis by enhancing RhoC accumulation and that higher RAB33A expression predicted poorer prognosis in patients with cervical cancer." (PMID 40000633, 2025). "RhoC GTPase together with its downstream regulator ROCK2 regulate the radiation response and supply the radio resistance in cervical cancer." (PMID 32443784, 2020). "Our results confirm that overexpression of RhoC induces radioresistance in cervical cancer cells and ROCK2 is the downstream target of RhoC in radiation response." (PMID 31488179, 2019). "Our data proposes a novel role of RhoC in cervical cancer radioresistance and presents evidence to support ROCK2 as the downstream effector of RhoC in radioresistance." (PMID 31488179, 2019). "Research from our laboratory (unpublished data) shows that RhoC and its downstream effector, ROCK2 regulates the radioresistance in cervical cancer." (PMID 31340863, 2019). "In vitro and clinical sample-based studies have been performed to understand its contribution to radiation response in cervical cancer and this is the first report to establish the role of RhoC and its effector ROCK2 in cervical cancer radiation response." (PMID 31488179, 2019). "Our results show that RhoC contributes to invasion, EMT, anoikis resistance, tumour growth and angiogenesis in cervical carcinoma." (PMID 19953094, 2010). "Collectively, our results showed that RAB33A induced non-canonical autophagy to stabilize RhoC, which in turn promoted metastasis in cervical cancer." (PMID 40000633, 2025). "Finally, findings herein strongly provide robust evidence, both clinical and cell line based, that RhoC and ROCK2 regulate radiation response and contribute to radioresistance in cervical cancer." (PMID 31488179, 2019). "In this report, we investigated the role of RhoC and ROCK2 in radioresistance in cervical cancer." (PMID 31488179, 2019).
cervical carcinoma (continued). "Thus, our study establishes that RhoC regulates radio-resistance in cervical cancer via ROCK2’s crosstalk with DNA repair assembly proteins, however the exact mechanism of regulation of ROCK2 by RhoC is still under investigation." (PMID 31488179, 2019). "Combined, our findings suggest a non-canonical signaling pathway for RhoC which regulates radiation response in cervical cancer via ROCK2 mediated DNA repair regulation." (PMID 31488179, 2019). "However, RAB33A inactivates RAB7, thereby inducing non-canonical autophagy to promote the accumulation of the RhoC protein, which in turn induces pseudopodia formation to promote cervical cancer metastasis." (PMID 40000633, 2025). "RhoC is degraded via canonical autophagy in nonmetastatic cervical cancer cells, and this process depends on two LIR motifs in RhoC." (PMID 40000633, 2025).
glioblastoma (8 papers, 2009 to 2025). The most malignant astrocytic tumor (WHO grade IV). "Beyond directly modulating epithelial and mesenchymal marker expression, elevated LACTB expression in glioblastoma was shown to reduce Rho-related GTP-binding protein RhoC (RHOC) protein levels, suppressing the RHOC/Cofilin signaling pathway." (PMID 39941048, 2025). "Finally, we demonstrated that circ-EPB41L5/miR-19a/EPB41L5 axis promotes the tumorigenesis of glioblastoma via activated RhoC and phosphorylated AKT." (PMID 31905344, 2020).
colon carcinoma (7 papers, 2014 to 2025). "For example, HOXD10 overexpression in colon cancer inhibits the RHOC/AKT/MAPK pathway, thereby suppressing cell proliferation, migration, and invasion." (PMID 40148674, 2025). "The expression of HOXD10 and RHOC was revealed by immunohistochemistry in disparate differentiation colon carcinoma tissues, and the dephosphorylation of AKT and MAPK pathways were detected by RT-PCR and western blot." (PMID 30683109, 2019). "HOXD10 was suppressed in colon adenocarcinoma cells, which down-regulated RHOC/AKT/MAPK pathway to enhance colon cancer cells apoptosis and constrain the proliferation, migration and invasion." (PMID 30683109, 2019). "However, the methylation status of HOXD10 and mechanism of action in colon cancer with RHOC and AKT pathway are still unclear." (PMID 30683109, 2019). "Finally, it is important to state that our findings do not exclude that miR-340-5p might target other molecules, such as RhoC and Cdc42, of potential importance for colon cancer cell migration and invasion." (PMID 33037251, 2020). "HOXD10 was inhibited in colon adenocarcinoma cells, thereby downregulating the RHOC/AKT/MAPK pathway to enhance apoptosis and restrain proliferation, migration, and invasion of colon cancer cells." (PMID 36213580, 2022). "In the colon cancer model, HOXD10 and RhoC were shown to negatively correlate with each other in both patient specimens and cell lines." (PMID 31340863, 2019). "The interaction of FMNL-3 with RhoC was seen to lead to increased MMP2, MMP9 and VEGF, consequently leading to increased invasion in colon cancer cell lines." (PMID 31340863, 2019).
osteosarcoma (7 papers, 2013 to 2022). A usually aggressive malignant bone-forming mesenchymal neoplasm, predominantly affecting adolescents and young adults. "In addition, RhoC was reported to be highly expressed in human osteosarcoma and associated with patients’ poor prognosis." (PMID 31443665, 2019). "The LncRNA AFAP1-AS1 promotes tumorigenesis and epithelial-mesenchymal transition of osteosarcoma through the RhoC/ROCK1/p38MAPK/Twist1 signaling pathway." (PMID 35179516, 2022). "This study demonstrates lncRNA AFAP1-AS1 is overexpressed in osteosarcoma and plays an oncogenic role in osteosarcoma through RhoC/ROCK1/p38MAPK/Twist1 signaling pathway, in which RhoC acts as the interaction target of AFAP1-AS1." (PMID 31443665, 2019). "AFAP1-AS1 is overexpressed in osteosarcoma and plays an oncogenic role in osteosarcoma through RhoC/ROCK1/p38MAPK/Twist1 signaling pathway, in which RhoC acts as the interaction target of AFAP1-AS1." (PMID 31443665, 2019). "For instance, the upregulation of lncRNA AFAP1-AS1 in osteosarcoma (OS) has been showed to promote the tumorigenesis, EMT, and consequent progression of OS cells through the regulation of the RhoC/ROCK1/p38MAPK/Twist1 axis." (PMID 35264071, 2022). "In our study, AFAP1-AS1 knockdown downregulated the expression levels of RhoC, ROCK1, phosphorylated p38MAPK, and Twist1 in osteosarcoma cells." (PMID 31443665, 2019). "Our results indicated that knockdown of AFAP1-AS1 led to decreased expression levels of RhoC and ROCK1 in osteosarcoma cell lines." (PMID 31443665, 2019). "Likewise, Shi and coworkers reported that knockdown of lncRNA AFAP1-AS1 inhibited tumorigenesis, epithelial-mesenchymal transition, and vasculogenic mimicry by sponging RhoC and altering the ROCK1/p38MAPK/Twist1axys in osteosarcoma cells." (PMID 32466537, 2020).